HDAC6 (histone deacetylase 6)
Diseases named in the same sentence as HDAC6 in open-access papers (continued):
Sharing a sentence is not in itself a finding about the gene and the disease.
glioma (continued). "These analyses showed that high levels of HDAC1 and HDAC6 correlated with decreased survival and advanced glioma grade in Rembrandt and TCGA, as well as additional cohorts." (PMID 32488056, 2020). "In our study, mRNA level of Cdk2, Cdk4 and Cdk6 down-regulated in MPT0B291-treated glioma cells indicating that HDAC6 inhibitor transcriptionally regulates those cyclin-dependent kinases." (PMID 33162824, 2020). "HDAC6 maintains glioma stem cells (GSCs) through GLI1 signaling and its specific inhibition, when combined with X-ray irradiation, suppresses the tumorigenic capacity of GSCs in vivo." (PMID 30804456, 2019). "Tubacin, the other miscellaneous HDAC inhibitor, is a specific for HDAC6 and it has been proposed to be useful because HDAC6 is known to be increased in certain high-grade gliomas." (PMID 30701185, 2018). "The analysis revealed that mRNA levels of both TDP-43 and HDAC6 were significantly higher in GBM samples than in low-grade glioma samples (p < 0.001)." (PMID 28915616, 2017). "HDAC6 expression was significantly increased in all gradesof gliomas, whereas HDAC7 and HDAC10 were significantly increasedonly in ODIII and GL tumors." (PMID 25791281, 2015). "Initially, the probe remains inactive, but upon activation by overexpressed HDAC6 in glioma cells, it releases methylene blue, which inhibits MAO A and restores the probe’s near-infrared fluorescence and photodynamic therapy activity when exposed to near-infrared light." (PMID 40565099, 2025). "The previous findings identify HDAC6 as a potential specific target for IDH1 mutant gliomas." (PMID 37528157, 2023). "Therefore, we tested the effect of HDAC6 and Hh inhibition, alone or in combination, on U87-MG glioma cell viability." (PMID 36982845, 2023). "HDAC6-mediated autophagy can result in “ciliophagy” in mouse tracheal epithelial cells and cholangiocarcinoma cells, and thus some glioma cilia may be driven by HDAC6-mediated autophagy whose signaling at cilia is a key regulator of glioma cell proliferation." (PMID 35359402, 2022). "In this study, HDAC6 expression was higher in glioma tumor than in normal tissues." (PMID 35359455, 2022). "HDAC6 inhibition disrupts glioma proliferation, but whether this effect is dependent on tumor cell primary cilia is unknown." (PMID 33915983, 2021). "Finally, we determined the effects of overexpressing HDAC6 on the frequency of ciliated glioma cells." (PMID 33915983, 2021). "The goal of the present study was to examine whether the effects of HDAC6 inhibition on glioma cell proliferation are dependent on tumor cilia." (PMID 33915983, 2021). "More recently, HDAC6 inhibitors have been found to induce the differentiation of glioma stem cells." (PMID 33915983, 2021). "Most astrocytes are quiescent in the normal brain, but it is unknown whether HDAC6 inhibitors would alter their proliferation in the glioma environment and whether this would impact tumor growth." (PMID 33915983, 2021). "Indeed, HDAC6 inhibitors have been shown to enhance glioma cell sensitivity to TMZ and radiotherapy." (PMID 33915983, 2021). "The study demonstrates that HDAC6 inhibitors are a potential target for the treatment of gliomas, and demonstrates that the combination of TMZ and TUB may be an effective strategy to facilitate the development of new clinical therapies." (PMID 34530730, 2021). "We next examined whether the effects of HDAC6 inhibitors on glioma cilia extend to normal neural cell types that harbor aaTub+ and ARL13B+ cilia, such as radial glial cells and GFAP+ astrocytes." (PMID 33915983, 2021). "It is unclear whether the HDAC6-inhibitor mediated changes in acetylation of normal astrocyte cilia represent a potential limitation of the use of HDAC6 inhibition for glioma." (PMID 33915983, 2021).
glioma (continued). "Together, these studies suggest that ciliated tumor cells may be more sensitive to HDAC6 inhibitors and raise an important and unanswered question as to whether HDAC6 signaling and promotion of tumor cell proliferation are dependent on cilia in glioma." (PMID 33915983, 2021). "To test whether the antiproliferative effects of HDAC6 inhibitors are dependent on tumor cell cilia, we generated patient-derived glioma lines devoid of cilia through depletion of ciliogenesis genes ARL13B or KIF3A." (PMID 33915983, 2021). "In this work, we show that HDAC6 is elevated in glioblastoma, the most malignant and common brain tumor in adults, in which its high levels correlate with poor patient survival and is more abundant in glioma stem cell subpopulation." (PMID 32488056, 2020). "Collectively, we demonstrated that the co-elevated expression of TDP-43 and HDAC6 positively correlated with the high-grade glioma and GBM, suggesting the TDP-43/HDAC6 could be a potential marker of prognosis in GBM." (PMID 28915616, 2017). "Our findings suggest that glioma growth may be slowed dramatically through treatment with HDAC6 inhibitors that hinder the proliferation and promote the differentiation of tumor cells, and that these effects may be highly dependent on HDAC6 expression and cilia frequency in individual tumors." (PMID 33915983, 2021). "Thus, HDAC6 promotion of cilia disassembly in glioma cells may require HDAC6 co-activation by other factors." (PMID 33915983, 2021). "Thus, a better understanding of the relationship between HDAC6 and ciliary signaling may lead to strategies that sensitize glioma cells to standard-of-care or novel therapies." (PMID 33915983, 2021). "However, glioma cell proliferation is significantly disrupted by HDAC6 inhibition." (PMID 33915983, 2021). "In addition, because HDAC6 inhibitors disrupt gliomagenesis by converting the phenotype of actively dividing glioma cells to more differentiated states, we examined whether this differentiation is also dependent on the presence of cilia." (PMID 33915983, 2021). "Importantly, our findings on the dependence of HDAC6 signaling on cilia may be relevant to the resistance of glioma to standard-of-care treatments." (PMID 33915983, 2021). "The mRNA expression of HDAC1, HDAC2, HDAC3, HDAC6 and PI3K/AKT1 was analyzed in GBM and low grade glioma tissues." (PMID 40297576, 2025). "Based on the RNA-seq results of U251 cells and glioma clinical data, we evaluated the expression levels of class I HDACs (HDAC1, 2, 3) and class IIb HDACs (HDAC6) in U251 cells treated with sodium butyrate." (PMID 40297576, 2025). "While no obvious HDAC candidate has yet emerged based on preferential baseline expression in IDHmut gliomas, others have shown that IDHmut gliomas are especially reliant on HDAC1 and HDAC6 activity." (PMID 41066183, 2025). "HDAC6 and USP9X protein levels were increased in glioma and GBM tissues compared to normal tissues in publicly available databases, including Human Protein Atlas." (PMID 40162736, 2025). "ISOX inhibits HDAC6, leading to a significant reduction in c-Jun N-terminal kinase (JNK) and c-Jun phosphorylation, preceding its inhibitory effect on the growth of glioma cells." (PMID 38612764, 2024). "Of the eleven annotated HDAC enzymes (HDAC1-11) only six are expressed in IDH1 mutant glioma tissue samples and patient-derived gliomasphere lines (HDAC1-4, HDAC6, and HDAC9)." (PMID 37528157, 2023). "This study identifies HDAC1 and HDAC6 as important and drug-targetable enzymes that are necessary for growth and invasiveness in IDH1 mutant gliomas." (PMID 37528157, 2023). "RNA-sequencing data from the public TCGA (The Cancer Genome Atlas) showed that HDAC4, HDAC5, HDAC6, HDAC8 and HDAC11 expression was significantly lowered in glioma (WHO grade II–IV) when compared to normal brain tissue." (PMID 37259375, 2023).
glioma (continued). "Except for HDAC6 (p = 0.367), HDAC9 (p = 0.870), and HDAC10 (p = 0.715), the majority of HDAC family expression levels correlated significantly with glioma grade." (PMID 34540896, 2021). "HDAC6 plays a role in promoting autophagy in glioma cells as a mechanism to promote resistance to TMZ and antitumor immunotherapy, and HDAC6 inhibitors were recently reported to disrupt the autophagic process at the primary cilia in other cancer types." (PMID 33915983, 2021). "Differentially expressed HDAC family members were identified with significance in ONCOMINE, namely the upregulated HDAC1 and HDAC6, as well as the downregulated HDAC4, HDAC5, and HDAC11 in glioma." (PMID 34540896, 2021). "Since HDAC6 inhibitors such as 738 are being explored for their anti-depressive effects in the adult brain, there could be a dual advantage in using HDAC6 inhibitors to target rapidly dividing tumor cells in glioma patients battling depression, which often accompanies this cancer." (PMID 33915983, 2021). "The brain tumor samples from ten low-grade glioma patients and ten GBM patients were analyzed by quantitative real-time PCR to measure the expression levels of TDP-43 and HDAC6 mRNAs." (PMID 28915616, 2017). "We also identified that HDAC1 and HDAC3expression levels were negatively correlated with survival time among gliomapatients, whereas the expression of HDAC4, HDAC5, HDAC6,HDAC11 and SIRT1 was positively correlated with survival time ofpatients with gliomas." (PMID 25791281, 2015). "Among all patients studied,the expression of HDAC1 and HDAC3 was inversely correlated withsurvival, whereas the expression of HDAC4, HDAC5, HDAC6,HDAC11 and SIRT1 was significantly and positively correlated withsurvival time of patients with gliomas." (PMID 25791281, 2015). "Genetic knockdown of HDAC6 inhibits cell proliferation, impairs glioma stem cell activity, and sensitizes glioma cells to temozolomide (TMZ), suggesting that HDAC6 inhibitors such as CAY10603 pose as potential specific (targeted epigenetic) therapies for GBM39,40." (PMID 40470218, 2025). "Ten glioma samples (5 IDH1 wildtype and 5 IDH1 mutant) were stained for various HDAC genes using internally validated antibodies (HDAC1, HDAC2, HDAC3, HDAC4, HDAC5, HDAC6 and HDAC7) and scored by a blinded neuropathologist (AK)." (PMID 37528157, 2023). "Low HDAC6 mRNA expression was significantly correlated with OS and DFS in patients with glioma." (PMID 35359455, 2022). "We first performed the univariate cox regression and found that the elevated expressions of HDAC7, HDAC3, and HDAC1 were associated with poor prognosis while increased expressions of HDAC6, HDAC5, HDAC4, and HDAC11 were favorable for prognosis in low-grade glioma." (PMID 36227941, 2022). "HDAC1/2/3/4/5/7/8/11 expression significantly varied across glioma stages, whereas HDAC6/9/10 expression did not." (PMID 35359455, 2022). "The role of HDAC6 and its function in gliomas have not been investigated with respect to tumor cell cilia." (PMID 33915983, 2021). "A highly conserved lncRNA, LINC00461, which functions as an essential regulator in glioma formation and regulates the expressions of genes such as DNA topoisomerase II Alpha (TOP2A), B-cell lymphoma 2 (BCL2), and integrin β3 (ITGB3), was identified to be remarkably downregulated by HDAC6 depletion." (PMID 35109908, 2022). "Moreover, low concentrations of HDAC6 inhibitors fail to inhibit the proliferation or induce the differentiation of glioma cells lacking cilia." (PMID 33915983, 2021). "Importantly, the HDAC6 inhibitors did not affect the proliferation or differentiation of glioma cells that we genetically modified unable to grow cilia." (PMID 33915983, 2021). "Overexpressing HDAC6 alone does not appear sufficient to reduce glioma cilia frequency or length." (PMID 33915983, 2021).
glioma (continued). "Surprisingly, overexpressing HDAC6 did not reduce cilia length or the frequency of ciliated glioma cells, suggesting other factors are required to control HDAC6-mediated cilia disassembly in glioma cells." (PMID 33915983, 2021). "Moreover, the differentiation of glioma cells that was induced by HDAC6 inhibition did not occur after the inhibition of cilia formation." (PMID 33915983, 2021). "Since breaking down cilia is required for cell cycle progression, and we did not observe cilia on glioma cells in the M phase of the cell cycle (data not shown), HDAC6 inhibitors may arrest glioma cells in a non-dividing, altered ciliated state characterized by a loss or reduction in ciliary aaTub." (PMID 33915983, 2021). "Moreover, HDAC6 inhibitors have been recently reported to drive stem-like cells into senescence or a differentiated neuronal state, which is consistent with the 738-induced increased expression of TUJ1, a marker of neuronal differentiation, that we observed in human and murine glioma cells." (PMID 33915983, 2021). "Thus, our data suggest that overexpression of HDAC6 alone may not be sufficient to promote cilia disassembly on glioma cells and that other factors may be required to drive cilia disassembly." (PMID 33915983, 2021). "Interestingly, genetic and enzymatic silencing of HDAC6 recapitulated these effects, suggesting that the selective suppression of HDAC6 may represent an alternative therapeutic approach in Notch3-dependent malignancies, such as T-ALL and glioma." (PMID 33003595, 2020).
Alzheimer disease (40 papers, 2010 to 2026). A progressive, neurodegenerative disease characterized by loss of function and death of nerve cells in several areas of the brain leading to loss of cognitive function such as memory and language. "The availability of iPSC-derived cortical neurons from AD patients and the discovery of SGK1 and HDAC6 as key targets based on pathogenic mechanisms would stimulate further research and drug discovery in Alzheimer’s disease." (PMID 40921794, 2026). "The histone deacetylase 6 (HDAC6) gene has been implicated in the pathogenesis of Alzheimer's disease and Parkinson's disease by linking together two protein degradation pathways (the ubiquitin proteasome system and autophagy)." (PMID 22577517, 2012). "HDAC6 has also been found to localise to Lewy bodies in Parkinson's disease patient brains and there is also evidence supporting a role for HDAC6 in Alzheimer's disease via its association with tau." (PMID 21677773, 2011). "In addition, several studies also reveal that HDAC6 is associated with the development of age-related disease, including Alzheimer’s disease." (PMID 33744850, 2021). "Moreover, HDAC6 and alterations in α-tubulin acetylation have been associated with several human disorders such as Alzheimer’s disease, Parkinson’s disease, Huntington’s disease, amyotrophic lateral sclerosis, and Charcot–Marie–Tooth disease (CMT)." (PMID 27957719, 2017). "This association of HDAC6 with amyloid pathology may indicate that the use of agents targeting this enzyme may lead to a more effective reduction of β-amyloid plaques and soluble toxic Aβ-oligomers in the brain of patients with Alzheimer’s disease." (PMID 37298694, 2023). "Ramalin alleviates Alzheimer's disease pathology by selectively inhibiting HDAC6, reducing BACE1 levels, and suppressing neuroinflammation through downregulation of the NLRP3 inflammasome and iNOS." (PMID 41488470, 2026). "A previous compound screen identified two molecules with histone deacetylase 6 (HDAC6) inhibitory activity that reduced Alzheimer's disease (AD)-like tau inclusions in a primary rat cortical neuron model seeded with AD brain-derived tau fibrils." (PMID 41330635, 2026). "Treatment with selective inhibitors targeting HDAC6 significantly improves Alzheimer's disease phenotypes, highlighting its potential as a promising therapeutic target warranting further investigation." (PMID 39834092, 2025). "Considerable evidence suggests that HDAC6 is closely related to amyloid and tau pathology, the two primary hallmarks of Alzheimer's disease (AD)." (PMID 37990786, 2024). "The use of HDAC6 inhibitors leads to cognitive deficit improvement, as shown in studies using mice models of Alzheimer’s disease." (PMID 37106761, 2023). "In recent years, the relationship between HDAC6 and Alzheimer’s disease has attracted considerable attention from researchers." (PMID 37298694, 2023). "In the last decade, there has been a genuine interest in the study of the HDAC6-inhibitory activity of potential therapeutic agents for the treatment of Alzheimer’s disease." (PMID 37298694, 2023). "Alzheimer’s disease (AD) is a progressive poly-factorial brain pathology in which σ-1, HDAC-6 activity, and oxidative stress (OS) have intertwined or synergistic neurodegenerative contributory roles." (PMID 37894975, 2023). "For example, HDAC6 inhibitor treatment reduced pathological tau hyperphosphorylation and improved cognitive behaviors in mouse models of Alzheimer’s disease." (PMID 32638097, 2021). "A specific HDAC6 inhibitor ameliorated Alzheimer’s disease phenotypes, and an HDAC8 inhibition repaired scopolamine-induced learning and memory impairments in animals." (PMID 30669368, 2019). "Reduction or inhibition of histone deacetylase 6 (HDAC6) has been shown to rescue memory in mouse models of Alzheimer’s disease (AD) and is recently being considered a possible therapeutic strategy." (PMID 28241840, 2017).